SRSF11 (serine and arginine rich splicing factor 11)
Description:
May function in pre-mRNA splicing.
Synonyms: p54; SFRS11; NET2; dJ677H15.2
Tractability: PROTAC: UniProt records ubiquitination sites on it; ubiquitination databases record sites on it; its protein half-life has been measured.
Gene: Protein-coding gene on chromosome 1 (70,205,670 to 70,253,052, forward strand). Ensembl gene ENSG00000116754.
Subcellular location: Nucleus
Subcellular location (Human Protein Atlas): Nuclear speckles
Pathways (Reactome):
Metabolism of RNA: Processing of Capped Intron-Containing Pre-mRNA; Transport of Mature mRNA derived from an Intron-Containing Transcript; mRNA 3'-end processing; mRNA Polyadenylation; mRNA Splicing - Major Pathway
Disease: Dengue Virus-Host Interactions
Gene Ontology:
Molecular function: protein binding; RNA binding; nucleic acid binding
Biological process: mRNA processing; RNA splicing
Cellular component: nuclear speck; nucleoplasm; nucleus
Genetic constraint (gnomAD): Loss-of-function variants: 4 observed, 39.05 expected, observed/expected ratio (o/e) 0.1, 90% interval 0.049 to 0.23. The upper end of that interval is the gene's LOEUF score, 0.23, which puts it in group 1 of 6, group 1 being the genes least tolerant of losing a copy. Missense variants: 323 observed, 509.52 expected, observed/expected ratio (o/e) 0.63, 90% interval 0.58 to 0.69. Synonymous variants: 194 observed, 193.55 expected, observed/expected ratio (o/e) 1, 90% interval 0.89 to 1.13.
Homologues: Orthologues: chimpanzee SRSF11 (100% identical), macaque SRSF11 (99% identical), mouse Srsf11 (95% identical), rat Srsf11 (95% identical), guinea pig SRSF11 (91% identical), dog SRSF11 (89% identical), tropical clawed frog srsf11 (82% identical), pig SRSF11 (76% identical), zebrafish srsf11 (68% identical), Drosophila melanogaster Srp54 (35% identical). Paralogues in human: SREK1 (49% identical).
Diseases named in the same sentence as SRSF11 in open-access papers:
SRSF11 is named in the same sentence as 23 diseases in open-access papers, as found by Europe PMC text mining. Sharing a sentence is not in itself a finding about the gene and the disease. The quoted sentences say what the papers report.
breast carcinoma (4 papers, 2020 to 2026). "J. OH33 reported that the decreased METTL3 expression leads to reduced SRSF11 expression in breast cancer (BRCA), Colon adenocarcinoma (COAD), lung adenocarcinoma (LUAD), and stomach adenocarcinomas (STAD)." (PMID 41584036, 2026). "For instance, some reports suggest SRSF11 promotes tumor growth in breast cancer, while others indicate it may act as a suppressor, depending on the context." (PMID 41584036, 2026). "Conversely, other Studies show that SRSF11 acts as a tumor suppressor in breast cancer." (PMID 41584036, 2026). "SRSF11 has also been previously identified to be involved in cell cycle-specific recruitment of telomerase to telomeres at nuclear speckles, thereby promoting breast cancer progression." (PMID 36230650, 2022). "For example, the β-deletion has been shown or speculated to be regulated by RMB10 in pancreatic cancer; NOVA1/PTBP1 in lung cancer; SRSF11, hnRNPH2, and hnRNPL in breast cancer; and MCPH1/BRIT1 in ovarian cancer." (PMID 33924498, 2021). "However, the exact regulatory mechanism of SRSF11 in breast cancer remains unclear and requires further investigation." (PMID 41584036, 2026). "Additionally, among splicing regulators frequently altered in breast cancers (in >5% of tumors), we found different members of SR protein family (such as SRSF1, SRSF2, SRSF3, SRSF4, SRSF6, SRSF9, SRSF10, SRSF11) with at least one predicted binding motif in the CD44 v10 region." (PMID 33143085, 2020).
ovarian carcinoma (4 papers, 2021 to 2026). A malignant neoplasm originating from the surface ovarian epithelium. "The role of SRSF11 in ovarian cancer prognosis remains controversial." (PMID 41584036, 2026). "So far, only one clinical analysis has suggested that SRSF11 may operate as a prognosis‐related SF in ovarian carcinoma." (PMID 36394206, 2022). "Several splicing factors may play key roles in ovarian cancer progression, including SPEN, SF3B5, RNPC3, LUC7L3, SRSF11, and PRPF38B80." (PMID 41584036, 2026). "Our splicing regulation network analysis showed some splicing factors might be correlated with prognosis-related AS events, including SPEN, SF3B5, RNPC3, LUC7L3, SRSF11 and PRPF38B, suggesting that these splicing factors could play crucial roles in ovarian cancer development." (PMID 34001978, 2021).
colorectal cancer (2 papers, 2022 to 2026). A primary or metastatic malignant neoplasm that affects the colon or rectum. "In colorectal cancer, SRSF11 interacts with PAK5, promoting alternative splicing of HSPA12A, which supports proliferation and invasion." (PMID 41584036, 2026). "In colorectal cancer, SRSF11 has been identified as a potential biomarker for FOLFOX resistance and therapy." (PMID 41584036, 2026). "Nonetheless, as a member of the serine/arginine‐rich protein family, the involvement of SRSF11 in colorectal cancer (CRC) is unknown." (PMID 36394206, 2022).
liver cancer (2 papers, 2021 to 2026). An epithelial or non-epithelial malignant neoplasm that arises from the liver. "Compared with the normal group, the expression of SRSF1, SRSF11 was found to significantly increase in the primary tumor of liver cancer." (PMID 34011971, 2021).
stomach adenocarcinoma (2 papers, 2024 to 2026). "Reduced SRSF11 and TRA2A expression is positively correlated with poor survival in patients with stomach adenocarcinoma." (PMID 39678510, 2024).
acute myeloid leukemia (1 paper, 2026). Acute myeloid leukemia (AML) is a group of neoplasms arising from precursor cells committed to the myeloid cell-line differentiation. "For example, a study on primary acute myeloid leukemia (pAML) identified hsa-miR-133 was significantly downregulated and regulated ZC3H15, BCLAF1, SRSF11, KTN1, PRPF40A, andGNL257." (PMID 41584036, 2026).
colon cancers (1 paper, 2017). "JMJD6 has been reported to be over-expressed in oral, breast, lung, and colon cancers and plays important roles in regulation of transcription through interactions with transcription regulator BRD4, histones, U2AF65, Luc7L3, and SRSF11." (PMID 29176719, 2017).
gastric cancer (1 paper, 2026). A primary or metastatic malignant neoplasm involving the stomach. "Elevated SRSF11 expression in gastric cancer also impacts immune cell infiltration, with high macrophage infiltration levels associated with poor outcomes." (PMID 41584036, 2026). "Aberrant SRSF11 expression is most consistently observed in HCC, CRC, gastric cancer, and glioma, where upregulation correlates with tumor progression, metastasis, and reduced overall survival." (PMID 41584036, 2026).
glioma (1 paper, 2026). A benign or malignant brain and spinal cord tumor that arises from glial cells (astrocytes, oligodendrocytes, ependymal cells). "n gliomas, SRSF11 modulates the splicing of CDC-like kinase 1 (CLK1), a cell cycle-related splicing factor, by promoting exon 4 inclusion that increases protein expression and activity." (PMID 41584036, 2026). "SRSF11 expression correlates with mRNA and protein levels in pediatric central nervous system tumors." (PMID 41584036, 2026).
myelodysplastic syndrome (1 paper, 2026). A clonal hematopoietic disorder characterized by dysplasia and ineffective hematopoiesis in one or more of the hematopoietic cell lines. "In myelodysplastic syndromes (MDS), high SRSF11 expression enhances its recruitment function while reducing the antagonistic effects of splicing suppressors, thereby promoting disease progression." (PMID 41584036, 2026).
oral cancer (1 paper, 2026). "SRSF3, SRSF10, and SRSF11 show increased expression as the disease progresses, indicating their involvement in oral cancer progression." (PMID 41584036, 2026).
cancer (6 papers, 2013 to 2026). A tumor composed of atypical neoplastic, often pleomorphic cells that invade other tissues. "This section explores the mechanisms underlying SRSF11 dysregulation and its impact on cancer-associated pathways." (PMID 41584036, 2026). "Despite substantial progress in understanding SRSF11-mediated splicing regulation, the mechanisms underlying its dysregulation and cancer-type specificity remain incompletely defined." (PMID 41584036, 2026). "We summarize established evidence from well-characterized cancers, identify gaps in current knowledge, and discuss the potential diagnostic, prognostic, and therapeutic implications of targeting SRSF11 in a context-dependent manner." (PMID 41584036, 2026). "METTL3-mediated downregulation of SRSF11 expression was associated with poor prognosis in these cancers." (PMID 39767561, 2024). "Based on its function as a nuclear speckle–targeting factor essential for telomerase association with telomeres, SRSF11 has been deeply explored in cancer research." (PMID 36160019, 2022). "In particular, cancer-associated miRNAs may downregulate SRSF11, altering its role in alternative splicing and influencing cancer progression." (PMID 41584036, 2026). "Some of these factors have already been linked with MDS or cancers in the literature, while others, such as SRSF11, may be candidate factors that need further validation." (PMID 24244432, 2013). "Titles and abstracts were screened to identify publications that investigated SRSF11 expression, regulation, or function in human cancers or experimental models." (PMID 41584036, 2026). "This review aims to provide a comprehensive overview of SRSF11 dysregulation in cancer, focusing on its mechanistic roles in splicing regulation, RNA metabolism, and tumor biology." (PMID 41584036, 2026). "By regulating the splicing of adhesion molecules and cytoskeletal regulators, SRSF11 promotes cancer cells detachment, migration, and invasion." (PMID 41584036, 2026). "Aberrant activity of SRSF11 in cancer frequently results in the upregulation of splice isoforms that support EMT22." (PMID 41584036, 2026). "We conducted a structured literature search of PubMed, Web of Science, and Scopus through July 2025 using the terms “SRSF11” OR “SFRS11” AND (“splicing” OR “RNA processing” OR “cancer”)." (PMID 41584036, 2026). "Collectively, these findings highlight SRSF11 as a promising but cancer-specific biomarker and therapeutic target, meriting further validation in broader tumor types." (PMID 41584036, 2026). "Its functions in different tissues and cancer types are not fully understood, making it challenging to classify SRSF11 as an oncogene or tumor suppressor." (PMID 41584036, 2026). "The expression levels of SRSF11 have shown prognostic value in several types of cancer." (PMID 41584036, 2026). "Cancer-specific post-translational modification patterns may enhance the ability of SRSF11 to drive oncogenic splicing programs, promoting malignancy." (PMID 41584036, 2026). "Non-coding RNAs that regulate SRSF11 expression have been dysregulated in specific cancers." (PMID 41584036, 2026). "In summary, this review integrates current mechanistic knowledge of SRSF11 across cancers, distinguishing confirmed from hypothetical pathways, and proposes a conceptual framework for translating these insights into precision, splicing-based therapeutic strategies." (PMID 41584036, 2026). "SRSF11 displays cancer-type-specific dysregulation with varying degrees of experimental validation." (PMID 41584036, 2026). "Despite growing evidence supporting the role of SRSF11 in cancer, several challenges remain." (PMID 41584036, 2026). "Despite extensive studies on SR proteins, the regulatory mechanisms driving SRSF11's cancer-specific roles remain unclear." (PMID 41584036, 2026).
cancer (continued). "Additionally, a study observed a correlation between METTL3 expression and the splicing factor SRSF11 in several cancer types, including breast invasive ductal carcinoma, lung adenocarcinoma, CRC, and GC." (PMID 39767561, 2024). "Moreover, how SRSF11 integrates with upstream signaling cascades or whether its modulation could be exploited therapeutically to target cancer-specific splicing events warrants further investigation." (PMID 41584036, 2026). "The serine‐rich proteins piqued our interest in examining the phosphorylation regulation between SRSF11 and PAK5 kinase, the latter of which is a Ser/Thr protein kinase that has oncogenic functions in diverse types of cancer." (PMID 36394206, 2022). "Collectively, these findings indicate that SRSF11 regulates tumor proliferation through multiple, cancer-type-specific splicing programs, rather than a single universal mechanism." (PMID 41584036, 2026). "Although SRSF11 is broadly upregulated in several malignancies, its biological function is not uniform across cancer types." (PMID 41584036, 2026). "SRSF11, a multifunctional nuclear protein also regulated by miR‐10b, among its other activities triggers alternative splicing of TERT, telomerase reverse transcriptase, gene critical for cancer stem cells self‐renewal." (PMID 26881967, 2016).
tumor (6 papers, 2021 to 2026). "Despite accumulating experimental evidence, important knowledge gaps remain, including incomplete mapping of SRSF11's upstream modifiers, inconsistent cohort-level associations, and limited mechanistic resolution across tumor types." (PMID 41584036, 2026). "The correlation analysis of the TCGA-LIHC cohort also suggested that SRSF11 expression was associated with gender, lymph node metastasis, and tumor differentiation." (PMID 36230650, 2022). "SRSF11 has emerged as a key splicing regulator with multifaceted but context-dependent roles in tumor biology." (PMID 41584036, 2026). "By disrupting regular splicing programs and inducing transcriptomic instability, abnormal SRSF11 expression and activity drive carcinogenesis, tumor progression, and therapy resistance." (PMID 41584036, 2026). "This highlights the need for tumor-type and molecular-subtype-specific analyses when evaluating SRSF11 as a biomarker or therapeutic target." (PMID 41584036, 2026). "Consistent with the cellular data, xenograft models corroborated these findings, with SRSF11 overexpression abrogating radiation-induced tumor suppression, whereas TET-induced silencing of SRSF11 recaptured the effect of IR." (PMID 41198615, 2025). "While SRSF family proteins are established orchestrators of oncogenic splicing programs in tumor initiation, metastasis, and therapeutic resistance, the mechanistic underpinnings of SRSF11—particularly its intersection with the DDR—have remained enigmatic." (PMID 41198615, 2025). "Because of the importance of EMT progression in tumour metastasis, we aimed to assess the impact of SRSF11 on E‐ and N‐cadherin expression levels, two important epithelial and mesenchymal gene markers of EMT progression." (PMID 36394206, 2022). "Based on the findings from the TCGA database, we investigated the differences in SRSF11 expression between the tumour and normal adjacent tissues from clinical CRC patients undergoing surgical resection." (PMID 36394206, 2022). "Further functional studies supported its pro‐metastatic role in CRC, as SRSF11 overexpression aided cell migration, invasion and wound healing ability in vitro, and promoted tumour metastasis in vivo." (PMID 36394206, 2022). "A composite SRSF11 × CDK1 × TERT signature may enhance the precision of tumor classification, particularly in HCC and CRC, where these splicing networks converge." (PMID 41584036, 2026). "Moreover, SRSF11 expression was correlated with tumor diameter and tumor number." (PMID 36230650, 2022). "Notwithstanding these open questions, the tumor cell death elicited by KAT2A/SRSF11 inhibition—selectively disabling HR without perturbing NHEJ—positions this pathway as a precision therapeutic vulnerability in radiation oncology." (PMID 41198615, 2025). "Importantly, an in vivo xenograft model further demonstrated the significant synergistic inhibitory effect of SRSF11 knockdown after IR in HCC, as reflected by results for tumor growth and tumor weight." (PMID 41198615, 2025). "In addition, survival-related AS events might be involved in tumor-related pathways including base excision repair and pyrimidine metabolism pathways, and some splicing factors might be correlated with prognosis-related AS events, including SPEN, SF3B5, RNPC3, LUC7L3, SRSF11 and PRPF38B." (PMID 34001978, 2021).
hematologic diseases (1 paper, 2013). "We found that SRSF11 protein is highly expressed in hematologic diseases." (PMID 24244432, 2013).
neurological disorders (1 paper, 2021). "Moreover, a recent genome-wide CRISPR-Cas9 screen has identified two additional factors, SRSF11 and RNPS1, that contribute to SRRM4-dependent microexon regulation, and these genes have also been implicated in ASD and other neurological disorders." (PMID 33482885, 2021).
SRSF11 also shares sentences with these, for which no sentence is quoted: hepatocellular carcinoma (2 papers); cognitive decline (1); colon adenocarcinoma (1); HIV-1 infection (1); lung carcinoma (1); lymph node metastases (1); pancreatic cancer (1); preeclampsia (1).